PGR (progesterone receptor)
Diseases named in the same sentence as PGR in open-access papers (continued):
Sharing a sentence is not in itself a finding about the gene and the disease.
tumor (continued). "Small tumor size, no involvement of axillary lymph nodes, high nuclear grade, low stage, negative ER and PgR status, positive HER2 status, high Ki67 labeling index (≥20%) and high APOBEC3B status were all significant in univariate analysis." (PMID 30093965, 2018). "The tumor was consistently unreactive to estrogen receptor (ER) and progesterone receptor (PR) and did not express human epidermal growth factor receptor 2 (HER2)." (PMID 29463294, 2018). "In breast cancer, the most used prognostic factors include patient characteristics (age and menstrual status), tumor features (tumor size, node status, and TNM stage), tumor tissue markers (estrogen receptor, progesterone receptor, HER-2 status, and ki-67 status), and genetic markers (BRCA1/2)." (PMID 29854028, 2018). "The patients with small tumor size (P = 0.024), high nuclear grade (P = 0.0038), negative ER and PgR status (P ≤ 0.0001), positive HER2 status (P = 0.032) and subtype (HER2-enriched, triple-negative; P ≤ 0.0001) were more likely to achieve pCR." (PMID 30093965, 2018). "Tumor cell content, DCIS content, HER2 immunohistochemical score of the invasive tumor and the DCIS, as well as relative expression of the mRNA markers ERBB2, ESR1, PGR and MKI67 and absolute Δ40-ddCq values are shown." (PMID 30342538, 2018). "In PAM50 analyses, tumours with a gene expression profile typical of luminal epithelial cells belong to the luminal subtype (of which there are two sub-categories), and are usually hormone receptor positive (ESR1+ PGR+)." (PMID 30248920, 2018). "In the current study, a strong association was found between high IL-10 and lower tumour grade, lower NPI level, positive ER and PgR status, negative Her-2 expression as well as with the non-TN type." (PMID 29256156, 2018). "Decisions about adjuvant treatment have traditionally been based upon prognostic factors such as age, tumor size, histological grade, proliferation, lymph node involvement, HER2 status, estrogen receptor (ER), progesterone receptor (PgR), and gene expression assays like Oncotype DX." (PMID 28528450, 2017). "TNBC is a heterogeneous group of tumours characterized by the absence of expression of histopathological markers such as the oestrogen receptor (ER), progesterone receptor (PgR) and ERBB2/HER2 oncogene." (PMID 29259228, 2017). "Triple negative breast cancer (TNBC), is defined as a type of tumor lacking the expression of estrogen receptor (ER), progesterone receptor (PR) and human epidermal growth factor receptor 2 (HER2)." (PMID 29261144, 2017). "IHC4+C is a composite score incorporating immunohistochemical parameters ER, progesterone receptor (PgR), HER2 and Ki67 (IHC4) with a clinical treatment score (C) of tumour size, grade, nodal status and type of endocrine therapy developed on samples from the TransATAC cohort." (PMID 28447240, 2017). "Of 4391 patients, 2711 (62%) were postmenopausal women and 20 (<1%) were men, 2337 (53%) were node positive, 2520 (57%) had grade 3 disease, 3196 (73%) had oestrogen-receptor-positive and/or progesterone-receptor-positive tumours, and 831 (19%) had HER2-positive tumours based on local assessments." (PMID 28600210, 2017). "SUVmax-high cancers were significantly more frequent in cancers with a large tumor size (>2cm, p<0.0001), nuclear grade 3 (p<0.0001), ER-negative (p = 0.0010), PgR-negative (p = 0.0013) and high Ki67 expression levels (p<0.0001)." (PMID 28886153, 2017). "Subsequent measurement of tumor biomarker mRNA expression to detect conversion revealed significant decreases in ESR1 and PGR mRNA and MKI67 upregulation (all p < 0.001) in MT compared to PT of all tumor subtypes and ERBB2 upregulation in MT from triple-negative PT patients (p = 0.023)." (PMID 28881657, 2017). "Among clinicopathological parameters, EFS was shorter in progesterone receptor (PR)-negative tumor (vs." (PMID 28057031, 2017).
tumor (continued). "To determine if our prognostic score was independent of age at diagnosis, tumor stage, estrogen- and progesterone-receptor status, we ran multivariate Cox regression force-entry with these factors including the prognostics scores as covariates." (PMID 28122328, 2017). "We found no PGR expression in the samples analyzed, except in 11 cases in the group with primary tumor and 3 cases in the group with relapsed tumor, which were weakly positive for ER." (PMID 28473663, 2017). "In our multi-institutional retrospective study, we found that the typical epithelioid cells of GP exhibited positive immunoreactivity for the progesterone receptor and pancreatic polypeptide, whereas tumor cells of NET G1 were negative for both markers." (PMID 28096810, 2016). "The discordance of HER2 status between CTCs and primary tumour has been demonstrated in other work, which also indicates that the phenomenon of heterogeneity between CTCs within individual patients, in regards to HER2, also exists as it does for ERα/PgR." (PMID 27189371, 2016). "By definition, these tumours are oestrogen receptor (ER) and progesterone receptor (PR) negative and negative for human epidermal growth factor receptor (HER2)." (PMID 27463681, 2016). "Some of the approved included; Cancer antigen 15-3 (CA 15-3) and Cancer antigen 27.29 (CA 27.29) kits that measure Mucin 1 (MUC1) levels in peripheral blood, assessment of carcino-embryonic antigen (CEA) levels in blood and ER, PgR, HER2 status of the primary tumour." (PMID 27189371, 2016). "A second finding of our study was that the annualized hazard of relapse in TP50 patients differs profoundly from that of patients whose tumors do not have simultaneous expression of ER and PgR in >50% of tumor cells (No-TP50)." (PMID 26910921, 2016). "MDA-MB-231 is a triple-negative breast cancer (TNBC), defined as a tumor negative for estrogen receptor (ER), progesterone receptor (PR) and human epidermal growth factor receptor 2 (HER2)." (PMID 27513518, 2016). "A high apoptotic index has been correlated with increased tumor grade, aneuploidy, high mitotic index, negative status for estrogen receptor (ER), and progesterone receptor (PR), tumor necrosis and increased lymphocyte infiltration." (PMID 27746811, 2016). "The GCH1 gene was also highly expressed in patients with ER or progesterone receptor (PR)-negative tumor status." (PMID 26814432, 2016). "Immunohistochemical staining was done on trephine biopsy tissue for breast markers which showed that the tumor cells are negative for estrogen receptor (ER) and progesterone receptor (PR), but showed strong membrane positivity for Her-2/neu." (PMID 27142269, 2016). "None of the tumor types expressed the estrogen or progesterone receptor (ER, PR), in line with previous observations that ER and PR are not expressed in tumors that developed in Wcre; Trp53F/F and Wcre;Cdh1F/F;Trp53F/F female mice." (PMID 27411687, 2016). "Third, immunohistochemical examination indicated that tumor cells were estrogen- and progesterone-receptor positive, while the smooth muscle cells in the venous walls were estrogen- and progesterone-receptor negative." (PMID 26858203, 2016). "To investigate whether the tumours with high immune gene expression (as represented by CD8A expression) show low levels of GATA3, ESR1 and PGR, we scattered each of these proteins against CD8A RNAseq counts." (PMID 26729235, 2016). "The tumor cells showed positive immunoreactivity for synaptophysin, chromogranin A, ER, PgR, and bcl-2 and negative (or almost negative) immunoreactivity for HER-2." (PMID 28105053, 2016).
tumor (continued). "TFF3 was higher in progesterone receptor-positive tumours as compared to progesterone receptor-negative tumours (Mann–Whitney U test, P=0.001) and in TFF1-positive tumours as compared to TFF1-negative tumours (Mann–Whitney U test, P=0.000)." (PMID 25900183, 2015). "In multivariate analysis, progesterone receptor expression in tumor cells was an independent negative prognostic factor for clinical failure (HR: 2.5, 95% CI: 1.2–5.2, p = 0.012)." (PMID 25723513, 2015). "Seromucinous tumor cells were positive for estrogen receptor (ER) and progesterone receptor (PgR) but negative for Napsin A, p504S, and HNF1B." (PMID 26075120, 2015). "Primary tumours from all lines were negative for progesterone receptor, Erb-b2/Neu and cytokeratin 5/6, but positive for epidermal growth factor receptor (EGFR)." (PMID 25633981, 2015). "The immunostaining results for the first tumor were as follows: estrogen receptor (ER), 94 %; progesterone receptor (PgR), 96 %; HER-2, negative and Ki-67, 10 %." (PMID 26722625, 2015). "Our results indicate that pregnancy significantly increases RANKL expression independent of PgR or other factors; both on the primary tumor and on normal breast tissue." (PMID 25849336, 2015). "The pathologic results were reviewed regarding the size, histological type, histological grade, estrogen receptor (ER) and progesterone receptor (PR) status, human epidermal growth factor receptor 2 (HER2), epidermal growth factor receptor (EGFR), and Ki-67 of the primary tumor." (PMID 25889560, 2015). "In the ER+/PgR+/HER2- group, the ER percentage ranged from 10% to 100% (median, 88.5%), and the PgR percentage ranged from 20% to 100% (median, 69.1%); none of the tumours expressed ER in the range of 1% to 9%." (PMID 25938238, 2015). "AKAP13 high tumours were more often lymph node positive (p = 0.033) and there was a trend towards negative progesterone receptor status (p = 0.071)." (PMID 26272591, 2015). "Immunohistochemistry of the tumor on review of paraffin embedded blocks showed neoplastic cells with triple negative results (estrogen receptor and progesterone receptor and Her-2/neu protein expression negative)." (PMID 26236516, 2015). "Tumor cells expressed smooth-muscle-actin, CD31, CD34, and progesterone receptor." (PMID 26351605, 2015). "The other tumor characteristics, including laterality, tumor size, lymph node (LN) status, American Joint Committee on Cancer (AJCC) stage, histologic grade, and estrogen receptor (ER) and progesterone receptor (PR) statuses, were similarly distributed between the two races." (PMID 25904050, 2015). "ER+/PgR-/HER2- tumours presented with a lower level of ER expression than ER+/PgR+/HER2- tumours, independent of the clinical tumour characteristics." (PMID 25938238, 2015). "Among the patients with PgR- tumours, 154 tumours were purely negative for PgR, and the PgR percentage of 212 tumours ranged from 1% to 19%." (PMID 25938238, 2015). "A previous study showed that ER+/PgR-negative (PgR-) tumours displayed more aggressive characteristics than ER+/PgR-positive (PgR+) tumours." (PMID 25938238, 2015). "Approximately 75–80% of BC tumours are positive for ER and/or PgR, whereas 20–25% of the tumours are receptor-negative or triple-negative when not overexpressing ER, PgR and HER2." (PMID 26540569, 2015). "The first is for the ∼25% of patients with oestrogen receptor- and progesterone receptor-negative tumours." (PMID 25900183, 2015). "TGFB3 mRNA expression was significantly lower in estrogen receptor-negative/progesterone receptor-negative/Basal-like/Grade 3 tumours." (PMID 26703884, 2015).
tumor (continued). "This acronym simply means that the tumour does not express oestrogen receptor (ER) and progesterone receptor (PR) and does not exhibit amplification of the human epidermal growth factor receptor 2 (HER2) gene." (PMID 26387133, 2015). "This showed that the top 8 NR, namely ERα, PGR, DAX1, TLX, PNR, RARγ, RARα and Rev-erbAβ provide the lowest error rate, highlighting these NRs as the most important variables for differentiating the two tumour clusters." (PMID 26280373, 2015). "Immunohistochemistry analyses revealed tumor cells negative for estrogen receptor (ER), progesterone receptor (PR), pan-cytokeratin (pan-CK), S100, vimentin and epithelial membrane antigen (EMA)." (PMID 25885768, 2015). "Knowledge of the expression of oestrogen-responsive biomarkers could assist in treatment stratification, because tumours that express TFF3, TFF1 and progesterone receptor are more likely to respond." (PMID 25900183, 2015). "Grade III tumours (P < 0.0001), larger tumours (≥5 cm, P < 0.0001) and tumours in pN3 (P = 0.002) were more common in the ER+/PgR-/HER2- group, whereas tumours in pN1 (P = 0.003) were more frequently observed in the ER+/PgR+/HER2- group." (PMID 25938238, 2015). "In our examination of 12 cases of duodenal GP, we found that epithelioid cells of GP exhibited positive reactivity for progesterone receptor and pancreatic polypeptide, whereas tumor cells of NET G1 were completely negative reactivity for both." (PMID 25886293, 2015). "In our study, there was a significant correlation between MMP-9 expression and lymph node metastases, advanced tumor stage as well as estrogen receptor negative and progesterone receptor negative hormonal status." (PMID 24993803, 2014). "Multivariate predictive models have been produced that incorporate tumor size, patient age, S phase and PgR as independent predictors, however, these were not classified by intrinsic subtype." (PMID 25202396, 2014). "While all tumors exhibited minimal to no staining for estrogen receptor α, progesterone receptor staining was observed for tumor grafts." (PMID 25542024, 2014). "The tumor was positive for both estrogen receptor (ER) and progesterone receptor (PR), and did not overexpress human epidermal growth factor receptor 2 (HER2)." (PMID 24533645, 2014). "Immunohistochemistry was also performed, revealing that the tumor cells were negative for estrogen receptor (ER), progesterone receptor (PR) and human epidermal growth factor receptor-2, and showed positive staining for S100." (PMID 25202382, 2014). "In univariate analyses, malignant axillary lymph nodes following US-guided FNA correlated with larger tumour size, higher tumour grade, presence of vascular invasion, absence of progesterone receptor expression, HER2 positivity, and Ki67>14%." (PMID 25207643, 2014). "ERα expression correlates with expression of progesterone receptor (PR), lower tumor grade, response to endocrine therapy, lower grade of aneuploidy, less frequent overexpression of HER-2 oncogene, bone metastases and slower rate of tumor recurrence." (PMID 24816249, 2014). "In this study, we found that ZNF545 was frequently downregulated in estrogen receptor-positive (ER+), progesterone receptor-positive (PR+) and human epidermal growth factor receptor 2-negative (HER2−) breast tumor tissues compared with paired adjacent non-tumor tissues." (PMID 25360542, 2014). "We investigated thyroid hormones levels in menopausal BrC patients because of their lack of estrogen and verified the action of T3 on genes regulated by E2 (TGFA, TGFB1, and PGR) and T3 (TNFRSF9, BMP6, and THRA) in primary BrC tissues exhibiting the early stages of tumor progression." (PMID 24701358, 2014). "There was a significant correlation between MMP-9 expression and lymph node metastases (p = 0.002), advanced tumor stage (p = 0.005) as well as both estrogen receptor negative (p = 0.005) and progesterone receptor negative (p = 0.003) hormonal status." (PMID 24993803, 2014).
tumor (continued). "Tumours were further examined for WHO histological type (ductal, lobular, and tubular) and hormone receptor status; estrogen receptor alpha (ERα), estrogen receptor beta (ERβ) and progesterone receptor (PgR)." (PMID 24708573, 2014). "There were significant differences between groups in tumor diameter, patterns of tumor enhancement, DMVD (edge-center), number of metastatic nodes, clinical stage, ER, PgR, Her2, Ki67, clinicopathological subtypes, chemotherapy, and endocrine therapy (P < 0.05)." (PMID 25224155, 2014). "The tumor cells showed triple negative immunoreactivity for estrogen receptor (ER), progesterone receptor (PR) and HER2/neu." (PMID 25274100, 2014). "HER2 amplification also correlated significantly with pathologic stage of disease, number of axillary nodes with tumor, histologic type, and absence of estrogen receptor (ER) and progesterone receptor (PgR)." (PMID 25276427, 2014). "Previous research demonstrated TH receptors in the nuclei of MCF-7 cells, while other works confirmed the presence of TH receptors in BrC tissue, but without correlation with other hormonal receptors (ER or progesterone receptor) or tumor progression." (PMID 24701358, 2014). "Prognostic factors commonly applied in breast cancer include age, tumor size, lymph node involvement, pathological grade, and status of HER-2, Ki-67, and several hormone receptors, including both estrogen receptor (ER) and progesterone receptor (PR)." (PMID 24906694, 2014). "Immunohistochemical analysis showed that the tumor cells were diffusely positive for ER, but negative for PgR." (PMID 24396451, 2014). "In univariate analysis, longer DFS was found for patients having tumours with BCL-2 positivity (P = 0.005), low grade (P = 0.001), ER (P = 0.017) and PgR (P = 0.045) positivity, CK5/6 negativity (P = 0.021), low TOPOIIα expression (P = 0.003) and high MVD (P = 0.000)." (PMID 25005788, 2014). "None of the pts changed HER-2 status, but 3 pts with ER positive in the primary tumour shifted to ER negative in the BM, 4 pts with PgR positive shifted to PgR negative in the BM and 1 pt with PgR negative in the PT showed PgR positive in the BM." (PMID 23634179, 2013). "We investigate here the association of continuous ER and PgR with DFS in patients randomized to tamoxifen or placebo regardless of locally determined ER and PgR tumour status." (PMID 23972025, 2013). "In univariate analysis, factors associated with locoregional recurrence after SSM and IBR were tumor size > 5 cm (P = 0.042) and negative progesterone receptor status (P = 0.004)." (PMID 23945398, 2013). "These correlations were independent of nodal status, tumor size, and progesterone receptor (PR) status in a multivariate analysis." (PMID 24077681, 2013). "In addition, the concordance rates were much higher for ER, PgR, and HER2 than Ki67, which again can be explained by more heterogeneous distribution within the tumor for Ki67, especially in ER/PR positive or grade 1–2 tumors." (PMID 23957561, 2013). "Tumorspheres were successfully isolated from all patient core biopsies, independent of the estrogen receptor α (ERα)/progesterone receptor (PR)/Her2/neu status or tumor grade." (PMID 22233382, 2012). "High tumour BCL2 protein expression was associated with lower grade of tumour (p = 4 × 10-9), presence of both oestrogen and progesterone receptor in tumours (p = 1 × 10-14 and 5 × 10-5 respectively), and lack of expression of CK5/6 (p = 0.002)." (PMID 23961365, 2012). "When the variables were combined in a Cox proportional hazards multivariate analysis ER protein expression remained significant independent of age, tumor size, nodal status, PgR, HER2, and ESR1 status." (PMID 22606272, 2012).